CAMP (cathelicidin antimicrobial peptide)
Diseases named in the same sentence as CAMP in open-access papers (continued):
Sharing a sentence is not in itself a finding about the gene and the disease.
infection (continued). "At 120-hours post infection, the relative CAMP mRNA remained significantly increased in the MΦ differentiated in 25D3, approximately 200–330 fold greater than in MΦ differentiated in the absence of 25D3." (PMID 29965969, 2018). "This efflux pump is highly relevant for in vivo survival; gonococci lacking mtr were completely outcompeted by the wild type strain in a competitive infection of the mouse genital tract and this was correlated with the levels of CAMP resistance in vitro." (PMID 25927010, 2015). "While there are abundant correlations between bacterial traits that increase CAMP resistance and affect virulence, it is in most cases yet to be proven during in vivo infection that resistance to CAMPs facilitates pathogenesis." (PMID 25927010, 2015). "A ΔpmrF S. Typhimurium strain cannot produce Ara4N, exhibits increased sensitivity to cationic antimicrobial peptide (CAMP)-mediated killing, and attenuated virulence in mice upon oral infection." (PMID 23166721, 2012). "After 25D3 supplementation, we found an increase in CAMP expression upon infection compared to biopsies prior to supplementation (P<0.05)." (PMID 21179490, 2010). "In addition, CAMP expression was ramped up 24 h post-MAP infection, which is expected as the cells try to respond to acute infectious triggers." (PMID 38732603, 2024). "Moreover, we found higher levels of CAMP in IL areas than in PL areas, which aligns with its role in responding to barrier disruption or infection." (PMID 39796069, 2024). "We noticed that genes encoding neutrophil granule proteins such as Ltf (lactotransferrin), Camp (cathelicidin antimicrobial peptide), and Ngp (neutrophilic granule protein) were all expressed at significantly higher levels pre-infection in young neutrophils compared to aged neutrophils." (PMID 37852965, 2023). "Some studies reported that NA could improve their ability of resistance to pathogen infection by improving the mice expression of antimicrobial peptide (CAMP and LF)." (PMID 35571917, 2022). "The ugd-arnBCADTEF locus is strongly activated by PhoP and should protect against CAMPs from the early stages of infection when Pve cells may face high CAMP concentrations in the apoplast." (PMID 33519782, 2020). "CAMP (also named LL-37), the sole know member of the cathelicidin family of peptide expressed in humans, is a multifunctional host defense molecule essential for normal immune responses to infection and tissue injury." (PMID 32867704, 2020). "Our study also provides mechanistic insights into the modulation of CAMP upon hMPV infection, which may apply to other types of infections." (PMID 29780383, 2018). "Interestingly, hMPV infection considerably repressed both the constitutive and vitamin D-induced CAMP expression." (PMID 29780383, 2018). "Further investigation is needed, however; in particular, the testing of HDACi in infection models is needed to determine whether HDACi can out-compete the capacity of some bacterial pathogens to down-regulate CAMP expression." (PMID 27025614, 2015). "Data are also lacking on the question of whether this combined co-treatment has additional synergistic effects on macrophage function during Mtb-infection and if it can synergistically inhibit intracellular Mtb growth via CAMP induction." (PMID 26133770, 2015). "Inactivating bacterial efflux pumps responsible for CAMP resistance could enhance the ability of the host CAMPs to clear infections, while at the same time increasing sensitivity to antibiotics." (PMID 25927010, 2015). "Though it is tempting to speculate that CAMP may be the dominant PhoQ-stimulant during systemic infection, it is important to remember that sensing may be redundant or host-compartment specific." (PMID 26002083, 2015). "Additionally, infection of macrophages with Mtb and other cell types with pathogens leads to the repression of the CAMP gene." (PMID 19607716, 2009).
infection (continued). "However, the pathways associated with drug resistance for antimicrobials, such as cationic antimicrobial peptide (CAMP) resistance and beta-lactam resistance had higher abundances at the PO stage, suggesting pathogens infection and antibiotic resistance occurring at the PO stage." (PMID 34603257, 2021). "Thus, the results above from in-depth mechanistic experiments demonstrated that MIR337-3p targeted/depressed upstream TLR4/MYD88 and STAT3 signaling and the downstream VDR antimicrobial pathways of CYP27B1/DEFB4A/CAMP, leading to an enhanced mycobacterial entry/infection and growth." (PMID 34912331, 2021). "Based on these reports, it has been speculated that directly inducing CAMP production in gastric mucosa is involved in the anti-inflammatory and anti-infection roles of VitD3, which further removes the microorganisms or bacteria from the mucosa and consequently reduces epithelial damage." (PMID 33194806, 2020). "In humans, CAMP (also known as hCAP18 or LL-37) is the sole member of the cathelicidin family of antimicrobial peptides (AMPs), evolutionary conserved molecules that form part of the innate immune system and serve as an important first line of defense against infections (as reviewed in15,16)." (PMID 30194425, 2018). "In response to injury or infection, keratinocytes upregulate CYP27B1 and VDR, leading to increased local production of active vitamin D, which in turn induces CAMP expression, thereby strengthening cutaneous immunity." (PMID 40649943, 2025). "Calcifediol treatment also reversed MAP effects at 48 h post-infection, with a decreased expression of both CYP27B1 and VDR and an increased relative expression of CAMP." (PMID 38732603, 2024). "One study suggested that infection with respiratory syncytial virus (RSV), a respiratory virus closely related to hMPV, increased the transcriptional expression of both CYP27B1 and CAMP in human tracheobronchial epithelial (hTBE) cells." (PMID 29780383, 2018). "As such, if Agr dysfunction becomes more widely accepted as being a critical determinant in the clinical outcome of infection, the accuracy of the VLT assay suggests that it should be used ahead of the plate based CAMP assay." (PMID 24498061, 2014). "At the 48 h post-infection time point, there was an increased relative expression of CYP27B1 and VDR (1.62 ± 0.32 and 1.27 ± 0.34, respectively) and a decreased relative expression of CAMP (0.29 ± 0.15)." (PMID 38732603, 2024). "At 24 h post-infection, there was a powerful upstroke in the relative expression of CYP27B1 and CAMP in MAP-infected THP-1 macrophages following TLR2 siRNA transfection with an average increase of 5.55 ± 0.82 and 24.47 ± 6.41 folds, respectively (p-value < 0.01)." (PMID 38732603, 2024). "This was also evident 48 h post-infection with a mean increase in the relative expression fold change of 10.02 ± 0.95 (p-value < 0.001) for CYP27B1, and 3.37 ± 0.71 (p-value < 0.05) for CAMP compared to the control, and the MAP-infected only groups." (PMID 38732603, 2024). "The infection levels in stomach tissues were quantified using the colony-forming assay, and the expression levels of the VDR and cathelicidin antimicrobial peptide (CAMP) in the gastric mucosa were analyzed by immunohistochemistry and western blotting." (PMID 36569092, 2022). "The increase in CAMP and RNASE7 mRNA levels during infection of metformin treated uroepithelial cells could be attributed to rapid transcriptional activation." (PMID 34584119, 2021). "Infection with DAP-R A8817 was unaffected by the presence or absence of the zebrafish CAMP hepcidin, whereas infection with the paired DAP-S strain A8819 caused greater mortality when hepcidin was inhibited." (PMID 33498191, 2021). "One possibility for the absence of CAMP mRNA but presence of cathelicidin protein at 24 hrs post infection is that upon infection with M. leprae the CAMP mRNA is downregulated yet the protein was already synthesized during differentiation." (PMID 29965969, 2018).
infection (continued). "No examples of Agr dysfunction have been reported amongst this group, indeed Agr function is believed to be critical to their emergence and virulence, suggesting that neither the VLT or the CAMP assay will be of use clinically for these types of infection." (PMID 24498061, 2014). "The gene group delineating infection in humans was functionally similar virulence factors, such as biofilm formation, ABC transporters, two-component system, lipopolysaccharide biosynthesis, cationic antimicrobial peptide (CAMP) resistance, secretion, and polyketide synthesis." (PMID 38029097, 2023). "Thus, our results do not exclude the possibility that GBS CAMP factor is required for colonization or infection in humans." (PMID 34908468, 2021). "In light of the increased prevalence of antibiotic resistant pathogens, these findings, which define novel mechanisms involved in the regulation of CAMP, suggest potential candidates for increasing innate immunity to infection that would not depend on antibiotic administration." (PMID 26404359, 2015). "As previously reported and confirmed by this work, S. Typhimurium ΔpmrA and ΔpmrF strains cannot produce Ara4N, are more sensitive to CAMP killing than are wild type (WT) bacteria and have attenuated virulence in mice upon oral, but not intraperitoneal (IP), infection." (PMID 23166721, 2012). "Despite generally low levels of CAMP-mediated RIVET reporter gene activation in vitro, macrophages were infected with the RIVET strains to determine if CAMPs can induce pagP or pmrH expression in host environments that Salmonella is known to encounter during infection." (PMID 22919691, 2012).
tumor (77 papers, 2009 to 2026). "Pseudotime analysis demonstrated that CAMP expression gradually increased as neutrophils differentiated toward tumor-associated states, whereas it significantly decreased at terminal states after RCT." (PMID 41878161, 2026). "At the single-cell level, CAMP showed significant differential expression in tumor-associated and RCT-related neutrophils." (PMID 41878161, 2026). "All tumors in NE/CAMP+aPD‐1 group completely regressed by Day 40, while only 40% and 60% tumor regression were observed in the groups of aPD‐1 alone and NE+aPD‐1 on Day 40, respectively." (PMID 39801750, 2025). "The NE/CAMP+aPD‐1 combination treatment showed superior anti‐tumor effect compared with each treatment alone and completely regressed subcutaneously implanted GBM as well as rechallenged one." (PMID 39801750, 2025). "To investigate the persistence of immune responses induced by the NE/CAMP+aPD‐1 combined treatment, we carried out a tumor rechallenge study." (PMID 39801750, 2025). "The intracerebral accumulation of NE/CAMP was observed in tumor of orthotopic GBM model mice, indicating that NE's migration ability into the brain was not affected by CAMP attachment." (PMID 39801750, 2025). "Based on these data, we evaluated the anti‐tumor effect of NE/CAMP in a subcutaneous GL261 mouse tumor model." (PMID 39801750, 2025). "This underscores the importance of further research to explore the relationship between CAMP expression and tumor development." (PMID 39339270, 2024). "It is worth noting that activating TLR8 signal in tumor cells can prevent tumor cells from producing CAMP, reverse the transformation of tumor‐induced initial type, and tumor‐specific T cells into senescent cells, and thus enhance antitumor immunity in vivo." (PMID 38063246, 2023). "Our data suggest that CAMP plays an important role in inhibiting tumor development during HCC development." (PMID 37958632, 2023). "PKA1α belongs to the serine/threonine kinase superfamily and is involved in tumor transformation and growth through the CAMP/PKA signaling pathway." (PMID 37476197, 2023). "The mRNA expression levels for CAMP gene were lower in HCC tumor tissues than in normal liver tissues." (PMID 35039485, 2022). "In the animal study, we found that mice with CAMP overexpressing cells had larger tumor volume than vector control, suggesting an oncogenic role of CAMP in vivo." (PMID 32365569, 2020). "The time-dependent increase in CAMP expression in the tumor microenvironment provides a novel targeted therapeutic option by blocking the positive feedback loop." (PMID 32365569, 2020). "In ovarian cancer, cancer cells induced CAMP expression in macrophages to promote tumor progression which indicated an important source of LL-37." (PMID 32365569, 2020). "Accumulating evidence suggested that human cathelicidin antimicrobial protein (CAMP), which is mainly expressed in host defense cells such as macrophages, is crucial not only in combating microorganisms but also promoting tumor growth." (PMID 32365569, 2020). "AFP/AFPR brings about Ca2+ influx, so the intracellular Ca2+ increases, then the intracellular CAMP correspondingly rises, enhancing protease A activity, prompting DNA synthesis, and achieving the purpose of tumor cell proliferation." (PMID 29805966, 2018). "The promotion of tumor proliferation of AFP/AFPR is dependent on the CAMP-PKA pathway and the induction of Ca2+ influx." (PMID 29805966, 2018). "The results indicated that low expression of CAMP/LL-37 correlated with histological differentiation and lymph node metastasis and also promoted tumor progression." (PMID 28427192, 2017). "Based on these findings, combination with other cytokines such as IFN‐γ as well as tumor cell‐specific antibodies may enhance the direct cytotoxic effect of NE/CAMP against GBM cells in vitro." (PMID 39801750, 2025).
tumor (continued). "Notably, the maximum tumor volume of the mice in the NE/CAMP +PD‐1 group was significantly smaller than other groups on Days 7 and 14 after tumor rechallenge." (PMID 39801750, 2025). "Due to the inability of NE/CAMPs to induce direct cytotoxicity against GBM cells, we hypothesized that the superior efficacy of NE/CAMP treatment may be due to the modulation of local and systemic anti‐tumor immune response." (PMID 39801750, 2025). "Tumor‐bearing mice were intravenously injected with NE/CAMPs or NEs alone twice after average tumor volume reached 70–80 mm3, and an intraperitoneal treatment of aPD‐1 was started 3 days after the second NE/CAMP treatment." (PMID 39801750, 2025). "The NE/CAMP+aPD‐1 group showed a rapid therapeutic response after the first aPD‐1 administration, and complete tumor regression was observed in 50% of mice on Day 28 after tumor inoculation." (PMID 39801750, 2025). "Even faster tumor regression was observed upon combining aPD‐1 with the NE/CAMP treatment." (PMID 39801750, 2025). "Based on these findings, we posit that the NE/CAMP+aPD‐1 combination induces potent and long‐term systemic immune activation, resulting in a superior anti‐tumor effect compared with other groups and induces complete regression of subcutaneously implanted GL261." (PMID 39801750, 2025). "This may be related to the epigenetic reprogramming caused by CAMP-induced PKA activation, which promotes differentiation of tumor stem cells and loss of tumor initiation ability." (PMID 38343637, 2024). "Notedly, CAMP may either serve as a tumor promoter or a tumor suppressor in different human cancers." (PMID 37958632, 2023). "Together, these results indicated that CAMP acted as a tumor suppressor in the development of HCC." (PMID 37958632, 2023). "A growing body of evidence illustrated that CAMP promoted tumor growth and invasion through angiogenesis initiation and recruitment of immune cells (e.g., monocytes, neutrophils, dendritic cells, mesenchymal stromal cells), while promoting wound healing ability and angiogenesis." (PMID 32365569, 2020). "Surgical removal of tumor decreased CAMP peptide serum level." (PMID 32365569, 2020). "Taken together, these results suggested that human CAMP/LL-37 might act as a tumor-suppressor in OSCC and DNA methylation might play roles during carcinogenesis via directly downregulating human CAMP promoter activity." (PMID 28427192, 2017). "Therefore, 2 cycles of preoperative CAMP therapy were administered to reduce the size of the tumor." (PMID 40959849, 2025). "Consequently, the time required for complete regression of secondary tumors was significantly lower in NE/CAMP +aPD‐1 group than in other groups, indicating that the combination treatment induced a stronger long‐term anti‐tumor immune response against subcutaneously inoculated GL261." (PMID 39801750, 2025). "Based on these findings, we hypothesized that activation of systemic anti‐tumor immune response by CAMP‐activated NE treatment could improve immunosuppressive environment, which concomitantly would synergize with ICI such as aPD‐1, resulting in a positive therapeutic outcome in case of GBM." (PMID 39801750, 2025). "Moreover, we screened several specific small molecule inhibitors using the CAMP database, which suggests that some of them may enhance anti-tumor activity by inducing pyroptosis." (PMID 37214439, 2023). "This implies that CAMP may act as a tumor suppressor in HCC." (PMID 37958632, 2023). "Similarly, in animal models CAMP treatment promoted tumor growth and metastasis." (PMID 27832772, 2016). "Since the combination of NE/CAMPs and aPD‐1 exhibited a potent anti‐tumor effect on GBM cells in vivo in the subcutaneous GL261 model, we investigated the potency of NE/CAMP+aPD‐1 combination therapy in an orthotopic GL261 GBM mouse model." (PMID 39801750, 2025).
tumor (continued). "We also found a significant reduction in the levels of tumor promoter GPs at the end of 4th week during 4-week intermittent fasting (POLK, CD109, CAMP, NIFK, SRGN), and 1 week after 4-week intermittent fasting (CAMP, PLAC1) compared with the levels before 4-week intermittent fasting." (PMID 33110154, 2020). "The low expression of CAMP/LL-37 was related to histological differentiation (p < 0.01) and lymph node metastasis (p < 0.01) in OSCC tissues, but was unrelated to age, gender and tumor size." (PMID 28427192, 2017). "The results also showed that the low expression of CAMP/LL-37 was related to histological differentiation, lymph node metastasis, and promoted tumor progression in OSCC tissues." (PMID 28427192, 2017). "Our previous results have demonstrated that CAMP attachment to NE significantly increases the release of myeloperoxidase (MPO) and tumor necrosis factor (TNF)‐α compared with untreated NEs showing activation and a shift towards anti‐tumor N1 phenotype in vitro." (PMID 39801750, 2025). "A number of interferon-stimulated genes (ISGs) were found to be highly induced in tumor compared to non-tumor samples, such as GBP1, CAMP, PTGS2, GOLIM4, IFIT3, MX1, LTF, and CYBB." (PMID 34400640, 2021).